DANCR (differentiation antagonizing non-protein coding RNA)
Diseases named in the same sentence as DANCR in open-access papers (continued):
Sharing a sentence is not in itself a finding about the gene and the disease.
nasopharyngeal carcinoma (6 papers, 2019 to 2021). A carcinoma arising from the nasopharyngeal epithelium. "In nasopharyngeal carcinoma, resveratrol was verified to suppress cancer progression via DANCR/PTEN pathway." (PMID 34722539, 2021). "Their study demonstrated that DANCR, acting as an oncogene in nasopharyngeal carcinoma, promoted nasopharyngeal carcinoma progression by interacting with STAT3 and enhancing JAK1 binding to STAT3 to strengthen IL-6/JAK1/STAT3 signaling." (PMID 33123287, 2020). "Hao's study suggested that DANCR overexpression promoted nasopharyngeal carcinoma cell proliferation and migration and inhibited apoptosis." (PMID 33123287, 2020). "And DANCR was responsible for nasopharyngeal carcinoma metastasis and hypoxia phenotype." (PMID 33123287, 2020). "DANCR could regulate the phosphorylation of AKT serine/threonine kinase and the protein expression of PTEN in nasopharyngeal carcinoma cells." (PMID 33123287, 2020). "DANCR could stabilize HIF-1α mRNA through interacting with NF90/NF45 complex, leading to nasopharyngeal carcinoma metastasis and invasion." (PMID 33123287, 2020). "In nasopharyngeal carcinoma cells (NPC), both lncRNA PVT1 and lncRNA DANCR can interact with HIF-1α to influence NPC progression." (PMID 33109235, 2020).
lung adenocarcinoma (5 papers, 2018 to 2020). A carcinoma that arises from the lung and is characterized by the presence of malignant glandular epithelial cells. "In addition, elevated DANCR expression was associated with poor prognosis in the patients with lung adenocarcinoma." (PMID 33123287, 2020). "This analysis illustrated that DANCR expression was highly upregulated in lung adenocarcinoma and squamous cell carcinoma compared to normal lung tissue." (PMID 33302540, 2020). "Moreover, our study found that silencing of DANCR reduced the protein levels of Smad2/3, which might be regulated by MDM2, since MDM2 has been documented to promote Smad2/3 activation in lung adenocarcinoma." (PMID 32423468, 2020).
papillary thyroid cancer (5 papers, 2019 to 2024). "The regulation of DANCR expression is still controversial in papillary thyroid cancer (PTC) and cervical cancer (CC)." (PMID 38877534, 2024). "Moreover, DANCR expression correlated with age and microcarcinoma, potentially influencing thyroid papillary carcinoma development." (PMID 38877534, 2024). "However, the expression profiles and biological relevance of DANCR in papillary thyroid cancer (PTC) have not yet been reported." (PMID 30910839, 2019).
esophageal squamous cell carcinoma (4 papers, 2020 to 2025). Esophageal squamous cell carcinoma (ESCC) is a type of esophageal carcinoma (EC) that can affect any part of the esophagus, but is usually located in the upper or middle third. "In a murine study, miR-4707-3p was found to interact with DANCR to regulate the expression of FOXC2 oncogene, in a zinc finger protein 750 (ZNF750) dependent manner, which affected esophageal squamous cell carcinoma angiogenesis." (PMID 41039543, 2025). "In metastasis, DANCR was recently found to be a direct target of zinc finger protein 750 (ZNF750), a tumor suppressor gene mutated/deleted in patients with esophageal squamous cell carcinoma (ESCC)." (PMID 36831169, 2023).
lymph node metastasis (4 papers, 2017 to 2022). "High DANCR expression was strongly associated with aggressive clinical variables patients with BC, such as lymph node metastasis and advanced TNM stage." (PMID 35150011, 2022). "The highest DANCR expression levels were associated with advanced tumor grades or lymph node metastasis." (PMID 31860165, 2020). "Correlation analysis of clinicopathological features and DANCR expression found that high DANCR expression was statistically correlated with vascular invasion, advanced T stage, lymph node metastasis and advanced TNM stage." (PMID 33123287, 2020). "DANCR overexpression was significantly correlated with lymph node metastasis and late clinical stage." (PMID 33123287, 2020). "DANCR expression was positively correlated with lymph node metastasis status, tumor stage, histological grade, and poor patient prognosis." (PMID 33123287, 2020). "We analyzed dysregulated DANCR expression and the clinicopathological characteristics of TNBC, and showed that expression of DANCR was significantly associated with TNM stage, histologic grade and lymph node metastasis." (PMID 28760736, 2017). "And high DANCR expression was correlated with TNM stage, histologic grade, and lymph node metastasis." (PMID 33123287, 2020).
melanoma (4 papers, 2021 to 2025). A malignant, usually aggressive tumor composed of atypical, neoplastic melanocytes. "DANCR is a melanoma oncogene that controls cancer-associated gene expression networks to promote human melanoma cell proliferation and migration." (PMID 41336739, 2025). "To investigate the role of DANCR in melanoma we first defined the transcriptional response to DANCR loss-of-function." (PMID 41336739, 2025). "Here, we aimed to clarify the role of DANCR played in melanoma progression and the underlying mechanisms." (PMID 37215458, 2023). "Regarding these and the important role of DANCR in several tumorigenesis, in present study, we explored the function of DANCR in regulating melanoma progression as well as the underlying molecular mechanism." (PMID 37215458, 2023). "Further analysis showed that high DANCR expression was associated with higher pathological T stage in melanoma." (PMID 37215458, 2023). "Thus, clinical evidences suggested that DANCR played a tumor-promoting role in melanoma progression and closely associated with the poor clinical prognosis in melanoma patients." (PMID 37215458, 2023). "We speculate that DANCR may act in a similar way in cancer stem-cells, such as the drug tolerant neural crest stem cell-like populations in melanoma, and that DANCR dependent re-activation of developmental programmes associated with NCC development could contribute to melanoma growth and metastasis." (PMID 41336739, 2025). "RT-qPCR profiling of four key DANCR target genes in A375 melanoma cells following DANCR depletion using two siRNAs led to changes in expression consistent with the SK-MEL-28 RNA-seq data, validating the specificity of these results." (PMID 41336739, 2025). "MITF thus regulates DANCR in a melanoma cell dependent manner whilst c-MYC activates DANCR across melanoma cells." (PMID 41336739, 2025). "We reveal that human DANCR is regulated by the cancer causing MITF and c-MYC transcription factors in melanoma, promotes human melanoma cell proliferation and migration and is associated with poor patient survival." (PMID 41336739, 2025). "Whilst MITF acts as a rheostat to govern the generation of different melanoma cell states in response to changes in the microenvironment, broad DANCR expression suggests additional modes of regulation." (PMID 41336739, 2025). "MITF and c-MYC, key melanoma transcription factors, regulate human DANCR expression and melanoma patients with high DANCR display significantly decreased survival." (PMID 41336739, 2025). "For further exploration, we employed qRT-PCR assay to clarify the expression of DANCR in different melanoma cell lines and found highest expression level of DANCR in A375 and SK-MEL-28 cells comparing to other cell lines." (PMID 37215458, 2023). "Further exploration revealed that except attenuating cell proliferation, downregulated DANCR also diminished angiogenesis of melanoma, which is an important way for supporting tumors with nutrients and oxygen." (PMID 37215458, 2023). "In this study, we analyzed the microarray data profiling from TCGA database and verified the tumor promoting role of lncRNA DANCR in melanoma progression." (PMID 37215458, 2023). "Consistently, expression of DANCR was negatively related to miR-5194 expression in human melanoma tissues." (PMID 37215458, 2023). "DANCR knockdown suppressed melanoma progression with a more significant suppression in vivo compared with it in vitro." (PMID 37215458, 2023). "DANCR-regulated processes and pathways are involved in both cancer and normal development and the results suggest that human DANCR may act to control melanoma cell proliferation and migration." (PMID 41336739, 2025). "Therapeutic targeting of DANCR would therefore be predicted to block the growth of all melanoma cell states and may have important implications for the development of new treatments targeting drug-tolerant cell subpopulations to prevent tumour relapse." (PMID 41336739, 2025).
melanoma (continued). "DANCR is a melanoma-associated lncRNA and conserved small non-coding RNA host gene that is expressed from equivalent regions in diverse vertebrate genomes and in a similar direction relative to the neighbouring USP46 and RASL11B protein coding genes." (PMID 41336739, 2025). "Altogether, the evidence suggests that human DANCR is a positionally conserved, clinically relevant oncogene that acts in a transcript-dependent manner to regulate gene expression programmes promoting proliferation and cell migration in melanoma." (PMID 41336739, 2025). "DANCR may therefore act within these cancer critical gene regulatory networks to control melanoma growth and metastasis." (PMID 41336739, 2025). "In our study, we found dysregulation of DANCR played an oncogenic role in melanoma progression." (PMID 37215458, 2023). "In according with the important role of angiogenesis in neoplasia, we hypothesized the function of DANCR in regulating angiogenesis in melanoma microenvironment." (PMID 37215458, 2023). "Moreover, CM from melanoma cells with DANCR knockdown diminished the ability of tube formation in HUVECs." (PMID 37215458, 2023). "Data from TCGA database also revealed that higher level of DANCR expression was accompanied with higher rate of mitotic cells, which indicated that DANCR might accelerate cell proliferation in melanoma cells." (PMID 37215458, 2023). "Clarifying the function of DANCR in melanoma development may open a new avenue for melanoma therapy and broadened the understanding of DANCR in promoting cancer progression." (PMID 37215458, 2023). "However, the function of DANCR in melanoma development is rarely studies." (PMID 37215458, 2023). "Moreover, upregulated expression of miR-5194 was found in melanoma cells with DANCR knockdown." (PMID 37215458, 2023). "To test if DANCR is directly regulated by MITF and c-MYC in melanoma we depleted these two transcription factors in multiple human melanoma cell lines using siRNA transfection and measured changes in gene expression using RT-qPCR." (PMID 41336739, 2025). "This suggests that human and zebrafish DANCR are conserved components of the MITF network in melanocyte development and melanoma." (PMID 41336739, 2025). "The results demonstrate that human DANCR is a MITF and c-MYC regulated lncRNA oncogene that promotes melanoma cell proliferation and migration and that melanoma patients with high DANCR expression have significantly decreased survival rates." (PMID 41336739, 2025). "However, the specific function of DANCR in melanoma remains unclear." (PMID 37215458, 2023). "Next, we used miR-5194 inhibitor to treat DANCR knockdown melanoma cells and found that miR-5194 inhibitor successfully reversed the reduction of VEGFB secretion and expression induced by DANCR downregulation." (PMID 37215458, 2023). "Therefore, DANCR might be a novel target for improving melanoma treatment." (PMID 37215458, 2023). "In summary, our results suggested that DANCR facilitated VEGFB expression and the sequential angiogenesis to enhance melanoma progression through directly binding with miR-5194." (PMID 37215458, 2023). "We found PRRT3-AS1 was significantly highly expressed in melanoma, BRAF, NF1, RAS mutants, and Triple WT tissues, whereas DANCR showed limited expression difference." (PMID 36211371, 2022). "According, DANCR is highly expressed across all four melanoma genomic subtypes (NRAS, NF1, BRAF, and triple negative) in The Cancer Genome Atlas (TCGA) genomic and transcriptomic data and in all melanoma cell subpopulations within a heterogeneous tumour model." (PMID 41336739, 2025). "DANCR depletion using siRNA did not affect expression of the embedded SNORA26 gene in melanoma cells, suggesting that the mature DANCR transcript is responsible for regulating these phenotypic changes." (PMID 41336739, 2025).
melanoma (continued). "To clarify the potential angiogenic factors involved in DANCR modulating interaction of melanoma cell and HUVECs, we implemented qRT-PCR assay to profile the different expressed angiogenic factors in A375 cells with or without DANCR knockdown." (PMID 37215458, 2023). "Our finding that DANCR is directly regulated by both MITF and c-MYC may explain its high expression in both proliferative (MITF-high) and invasive (c-MYC-high) transcriptional states in melanoma." (PMID 41336739, 2025). "DANCR may play an essential role in melanoma downstream of MITF and c-MYC irrespective of tumour genomic status." (PMID 41336739, 2025). "DANCR is highly expressed in all known cell states in melanoma and in all four tumour genomic subtypes suggesting that it may play an essential role in melanoma irrespective of tumour heterogeneity and genomic status." (PMID 41336739, 2025). "siRNA mediated depletion of DANCR targets the mature processed lncRNA transcript and did not affect the levels of SNORA26 suggesting that the embedded small RNAs do not play a significant role in controlling proliferation and migration in melanoma." (PMID 41336739, 2025).
retinoblastoma (4 papers, 2019 to 2022). A malignant tumor that originates in the nuclear layer of the retina. "LncRNAs PVT1, AFAP10AS1, HOTAIR, BANCR, H19, DANCR and LINC00202 were up-regulated in retinoblastoma tissues while MT1JP and BDNF-AS were down-regulated." (PMID 32514246, 2020). "The ectopic overexpression of DANCR indicated poor overall survivals and DFS for retinoblastoma patients." (PMID 33123287, 2020).
Sepsis (4 papers, 2020 to 2025). Sepsis is defined as life-threatening organ dysfunction caused by a dysregulated host response to infection. "DANCR exhibits aberrant expression in acute kidney injury related to sepsis and is associated with immune tolerance in kidney transplantation." (PMID 38609873, 2024). "Several studies have highlighted the detrimental role of DANCR in sepsis-related disorders." (PMID 41394397, 2025).
atherosclerosis (3 papers, 2022 to 2024). A disease characterized by the build-up of fatty material and calcium deposition in the arterial wall resulting in partial or complete occlusion of the arterial lumen. "DANCR could be a potential diagnostic marker to distinguish atherosclerosis patients from healthy individuals." (PMID 35235755, 2022). "Given that DN often leads to microvascular diseases, atherosclerosis, and other cardiovascular diseases, DANCR’s involvement in atherosclerosis has been established, and it functions as a predictive biomarker." (PMID 38609873, 2024). "In the current study, DANCR was found to be highly expressed in the serum of patients with atherosclerosis." (PMID 35235755, 2022). "Future studies will use more cells that contribute to atherosclerotic lesion formation (such as endothelial cells) to evaluate the role of DANCR in atherosclerosis." (PMID 35235755, 2022). "This study uncovered that DANCR might be a diagnosis predictor and a potential target for treating atherosclerosis." (PMID 35235755, 2022). "Based on the previous study and present data, it is speculated that DANCR may involved in the progression of atherosclerosis through miR-335-5p/JAG1/Notch signaling." (PMID 35235755, 2022). "Finally, the detailed mechanism of DANCR in atherosclerosis needs to be further explored in future studies." (PMID 35235755, 2022). "In the present study, DANCR was shown to be highly expressed in the serum of patients with atherosclerosis compared to healthy controls, suggesting that DANCR may promote the process of atherosclerosis." (PMID 35235755, 2022). "Loss-of-function assays indicated that DANCR knockdown weakened the proliferation and migration of VSMC cells, implying that downregulation of DANCR may contribute to the prevention of atherosclerosis." (PMID 35235755, 2022). "DANCR expression could distinguish patients with atherosclerosis from healthy individuals with a high area under the ROC curve (AUC), sensitivity, and specificity." (PMID 35235755, 2022). "However, the clinical and functional role of DANCR with involvement in atherosclerosis disease pathogenesis remains unclear." (PMID 35235755, 2022). "This study aims to investigate the clinical role and functional role of DANCR in the pathogenesis of atherosclerosis and explore the potential molecular mechanisms, wherein the expression pattern of DANCR was measured in the serum of patients with atherosclerosis and healthy controls." (PMID 35235755, 2022). "However, the detailed role of DANCR in atherosclerosis remains elusive." (PMID 35235755, 2022).
cholangiocarcinoma (3 papers, 2021 to 2024). A carcinoma that arises from the intrahepatic biliary tree (intrahepatic cholangiocarcinoma) or from the junction, or adjacent to the junction, of the right and left hepatic ducts (hilar cholangiocarcinoma). "In cholangiocarcinoma (CCA) cells, DANCR binds to EZH2 to facilitate histone methylation of the FBP1 promoter, ultimately suppressing FBP1 expression via epigenetic mechanisms." (PMID 38877534, 2024). "Downregulation of DANCR inhibited the levels of VEGF-C and VEGF-A in cholangiocarcinoma cell lines." (PMID 35573683, 2022).
myocardial infarction (3 papers, 2022 to 2025). Gross necrosis of the myocardium, as a result of interruption of the blood supply to the area, as in coronary thrombosis. "Overexpression of DANCR decreased myocardial infarct size and enhanced cardiac contractile function in AMI mice." (PMID 39546553, 2024). "Previously, DANCR has been reported to have substantial contributions to cancer progression, yet study has demonstrated its protective role in hypoxia-induced myocardial infarction." (PMID 41394397, 2025). "However, the role of DANCR in myocardial infarction is not fully understood." (PMID 39546553, 2024). "A similar role of DANCR was observed in cardiomyocytes, as its upregulation of DANCR could inhibit apoptosis and promote autophagy to protect cardiomyocytes from endoplasmic reticulum stress that leads to the conduces to the etiopathogenesis of myocardial infarction." (PMID 35235755, 2022).
postmenopausal osteoporosis (3 papers, 2017 to 2021). Metabolic disorder associated with fractures of the femoral neck, vertebrae, and distal forearm. "In addition, DANCR expression was found upregulated in circulating monocytes, and increase their bone-resorbing activities in osteoporotic patients and identified as a potential biomarker of postmenopausal osteoporosis." (PMID 34960006, 2021).
triple-negative breast carcinoma (3 papers, 2017 to 2020). An invasive breast carcinoma which is negative for expression of estrogen receptor (ER), progesterone receptor (PR), and human epidermal growth factor receptor 2 (HER2). "In these studies, intravenously injected Arg-Gly-Asp and polyethylene glycol (RGD-PEG) labeled ECO NPs delivered siRNA targeting β3 integrin, DANCR, and eIF4F expression to reduce metastasis of triple-negative breast cancer and chemotherapeutic resistance." (PMID 33158243, 2020). "DANCR-induced RXRA phosphorylation suppressed RXRA-inhibited PIK3CA transcription in triple negative breast cancer cells and ultimately activated the downstream PI3K/AKT signaling." (PMID 33123287, 2020). "Thus, our study demonstrated that targeting DANCR expression might be a viable therapeutic approach to treat triple negative breast cancer." (PMID 28760736, 2017).